ATM (ATM serine/threonine kinase)
Diseases named in the same sentence as ATM in open-access papers (continued):
Sharing a sentence is not in itself a finding about the gene and the disease.
infection (continued). "Consistent with the infection being sufficient to efficiently inhibit ATM signaling, we show that HHV-6B replication in infected cells is not further increased upon depletion of NBS1 or ATM." (PMID 38177923, 2024). "Since the MRN complex recruits ATM to the damage site, this study used A-TLD1 patient cell lines expressing a truncated form of Mre11 to demonstrate that complete activation of ATM during infection was dependent on Mre11." (PMID 38932138, 2024). "The increase of phospho-53BP1 over time of infection coincides with the increase of phospho-ATM, as it is known that 53BP1 is activated by ATM, which becomes significantly active from 4 hpi onwards." (PMID 38433244, 2024). "Overall, these findings suggest that ATM-AVI is potent against Enterobacterales isolates from various infection sources and its activity has been maintained over the years." (PMID 37998793, 2023). "HBoV1 infection initiates a DDR with activation of all 3 phosphatidylinositol 3-kinase–related kinases (PI3KKs), including ATM (ataxia telangiectasia mutated), ATR (ATM and RAD3 related), and DNA-PKcs (DNA-dependent protein kinase catalytic subunit)." (PMID 36719192, 2023). "Globally, MIC frequency distribution revealed that the MIC90 values for ATM-AVI against isolates from the infection sources ranged from 0.12 to 0.25 μg/mL, and those for aztreonam ranged from 64 to 128 μg/mL." (PMID 37998793, 2023). "A similar trend was observed against isolates from all infection sources, with ≥99.1% of isolates inhibited by ATM-AVI at ≤8 μg/mL globally and across all regions." (PMID 37998793, 2023). "Overall, ≥99.7% of isolates were inhibited by ATM-AVI at ≤8 μg/mL across all infection sources (RTI, UTI, SSTI, BSI, and IAI) globally and in all regions." (PMID 37998793, 2023). "Depleting ATM kinase by generating mutant cell lines or chemical inhibition of ATM reduces HSV-1 productive infection." (PMID 36140380, 2022). "Protoparvovirus minute virus of mice (MVM) infection activates the ATM pathway, ATR, and DNA-PKcs with its accessory proteins, i.e., the Ku70/Ku80 heterodimer, which accumulate in the virus replication centers, depending on the cell types." (PMID 34878919, 2022). "In our studies, MC was induced between 12 and 15 h after infection and most of the infected cells presented a well-defined MC phenotype at 24 h, before the previously reported ATM and Chk2 activating phosphorylation." (PMID 35412344, 2022). "To further evaluate the effect of these pathways on γ-H2AX expression, we treated RD cells with an ATR inhibitor (VE-821), DNA-PK inhibitor (KU 57788), or ATM inhibitor (KU 55933) at 2 h post infection with EVA71 (MOI = 2)." (PMID 35067196, 2022). "We observed distinct DDR kinase responses for uninfected versus infected cells, including a biphasic DDR to infection dominated by an initial Chk2 response to incoming viral DNA, which then transitioned to an ATM-dominated response to replicating viral DNA." (PMID 33563816, 2021). "By 2 hpi, the results mirrored d109 infection, where knockout of ATM strongly reduced the phosphorylation of Chk2 (lane 8)." (PMID 33563816, 2021). "Upon infection, H2AX and RPA32 are phosphorylated, and the signals are passed through phosphoinositide 3-kinases ATM (Ataxia telangiectasia mutated), ATR (ATM- and RAD3-related), and DNA-PKcs (DNA-dependent protein kinase catalytic subunit), respectively." (PMID 34220786, 2021). "By 8 hpi with both 7134 and 7134R infection, ATM and H2AX phosphorylation were only weakly affected by MRE11A knockout (lanes 9 and 15), arguing that there were redundant pathways for their activation." (PMID 33563816, 2021). "HBoV1 infection activates ATM, ATR and DNA-PK, which play significant roles in viral DNA replication." (PMID 34220786, 2021). "This indicates some specificity in ATM substrates between infection and cellular DNA damage responses." (PMID 33563816, 2021).
infection (continued). "Infection of PΦ with Rv resulted in the activation of DNA-PKcs, albeit to much lower levels and at later time points compared with the ATM." (PMID 32223892, 2020). "Kinase-motif analysis reveals temporal activation patterns of certain protein kinases, with several CDKs/MAPKs immediately active upon the infection, and basophilic kinases, ATM, and ATR engaging later." (PMID 32859902, 2020). "This encouraged us to investigate the possibility of utilizing ATM inhibitor toward adjunct HDT for TB with the help of murine infection model." (PMID 32223892, 2020). "On the other hand, infection by Rv led to significant activation of ATM-Chk2 pathway in both RAW and PΦ cells, suggesting occurrence of DSBs in the host nuclei." (PMID 32223892, 2020). "Addition of ATM inhibitor enhances isoniazid mediated Mtb clearance in macrophages as well as in murine infection model, suggesting its utility for host directed adjunct therapy." (PMID 32223892, 2020). "In a chronic mice infection model, Mtb infected lungs showed significant DSBs and activation of ATM." (PMID 32223892, 2020). "Taken together, all members of the alpha-, beta- and gamma-herpesvirus subfamilies have in common that they activate the ATM response at later time points during infection, indicating an important role of ATM activation for viral replication." (PMID 31500286, 2019). "We thus monitored ATR and ATM activation in HeLa cells collected 8 h after infection with DH10B hosting the BACpks or the vector or after treatment with mitomycin C (MMC)." (PMID 29559578, 2018). "For example, early in infection, ATM and the MRN complex localise to the nuclear sites of HSV-1 replication." (PMID 30440001, 2018). "Shortly after initial infection, the host cell initiates a DNA damage response (DDR), seen as the phosphorylation of a number of well-characterized ataxia telangiectasia mutated (ATM) and ATM- and Rad3-related (ATR) substrates (6, –, 8)." (PMID 29593045, 2018). "Consistent with our overall model, we have previously demonstrated that an ATM inhibitor applied during infection specifically reduced virus replication." (PMID 30028293, 2018). "Another study revealed that activation of the ATM pathway was observed following primary infection of EBV in human B cells." (PMID 29144413, 2017). "In vitro infection of immortalized nasopharyngeal epithelial cell lines with a recombinant EBV was also followed by the down-regulation of ATM, and only the EBV-infected cells showed a defective DNA damage response following γ irradiation." (PMID 29144413, 2017). "We have demonstrated that the related kinase ATR acts to promote virus replication as part of an infection-induced cytoplasmic ATR/ATM-dependent response." (PMID 28467896, 2017). "Other pathways were altered in both MP12 and ZH548 infection, including G2/M DNA damage checkpoint, ATM signaling, mitochondrial dysfunction, role of PKR in interferon induction and antiviral response, and ILK signaling." (PMID 29085037, 2017). "Herpes simples virus 1 (HSV-1) infection of dividing cells induces the ATM (ataxia telangiectasia mutated) pathway of DDR and nullification of components of this pathway reduces the infection of HSV-1." (PMID 27314325, 2016). "Blocking ATM activation, which is an early response to infection, decreases transcription of ER stress response proteins, but ATM has limited impact on production of ROS and virus titers." (PMID 26938301, 2016).
infection (continued). "Collectively, these results demonstrate that among the multiple autophagy-inducing pathways during infection, ER stress signaling is more important to viral replication and protection of cells than either ATM or ROS-mediated signaling." (PMID 26938301, 2016). "When both ATM and ATR were deficient, the efficiency of dl366* infection was increased by 271-fold (ln(fold) = 6) and E4orf4 further increased replication efficiency by close to 3.3-fold (ln(fold) = 1.11)." (PMID 26867009, 2016). "Activation of both ATM and Chk1 phosphorylation occurred in WT cells infected with dl366*, whereas upon infection with dl366*+E4orf4, ATM phosphorylation at S1981 and Chk1 phosphorylation at three phospho sites were reduced." (PMID 26867009, 2016). "The activation and activity of ATM before induction of autophagy indicates that ATM is upstream of infection-provoked autophagy signaling." (PMID 26938301, 2016). "The increase of ATM activity during the early stages of infection suggests that ATM is upstream of virus-triggered autophagy." (PMID 26938301, 2016). "ATM and the γH2AX response have also been studied in the context of infection by other herpesviruses." (PMID 26817608, 2016). "CPE were detected more clearly during dl366* infection of A-T cells reconstituted with the empty vector, which lack ATM, than in A-T cells expressing WT ATM (compare squares b3 and b1)." (PMID 26867009, 2016). "Our discovery that HCMV can be forced out of latency by pharmacological manipulation suggests new avenues to eradicate infection by combining ATM and NF-κB activation with immune- or drug-based approaches aimed at killing HCMV-infected cells." (PMID 25846574, 2015). "Infection with B19V induces a broad range of DNA damage responses by activating three upstream kinases: ATM, ATR, and DNA-PKcs." (PMID 24859341, 2014). "We already knew by WBs that the HO fusion protein varies little throughout the time course of infection, but its activity seems to be limited to the first hour, after which the enzyme is phosphorylated by ATM/ATR and appears to be inhibited." (PMID 24655462, 2014). "The subsequent induction of cell cycle checkpoints and activation of ATM/ATR/DNAPKcs pathways have been reported to accompany infection by a number of different viruses." (PMID 24859341, 2014). "Another example is seen in the case of SV40 infection, where infection results in activation of ATM and endogenous ATM substrates." (PMID 25340830, 2014). "To further demonstrate the inhibitory role of ATM on infection we performed another assay in which cells are transfected with siRNA against ATM and infected with L. monocytogenes." (PMID 25340842, 2014). "In summary, though there are some viruses that do not use DDR for their replication (i.e., Ad5), there are numerous viruses that induce DDR pathways and require ATM or other PI-3-like kinases for productive infection." (PMID 24859341, 2014). "Consistent with resection mediating ATR activation early during infection, ATM inhibition prior to 20 hpi decreased ATR activation whereas inhibition from 20 to 48 hpi did not affect ATR kinase function." (PMID 25474690, 2014). "Conversely, similar percentages of G1 and S phase cells to those observed in asynchronous, mock-infected BSC40 cells were observed when ATM was inhibited for the duration of infection." (PMID 25474690, 2014). "Infection of cells by polyomaviruses and papillomaviruses is accompanied by intense ATM and ATR activation." (PMID 25474690, 2014). "In contrast, inhibition of ATM during the late phase of infection only very weakly attenuated the SV40-induced S phase arrest." (PMID 25474690, 2014). "In contrast, the total levels of ATM are decreased in both STAT-5α or STAT-5β knockdown cells after infection and 72 hours of differentiation in high-calcium media." (PMID 23593005, 2013). "The graph reveals that ATM inhibition reduced unit length SV40 product by at least 5-fold compared to the DMSO control infections." (PMID 23592994, 2013).
infection (continued). "Inhibition of ATM either early or throughout infection reproducibly reduced the level of total viral DNA and monomeric DNA products by 50–80% relative to that generated in the DMSO-treated control infection." (PMID 23592994, 2013). "To assess the impact of ATM inhibition during each phase of infection on viral chromatin replication, we visualized viral replication centers and DNA damage signaling in each infected cell population using immunofluorescence microscopy." (PMID 23592994, 2013). "Here we demonstrate that ATM also has a critical role in the induction of IL-8 by HCMV as infection of ATM -/- cells with wild type HCMV resulted in considerably lower levels of secreted IL-8 compared to the similar infection of normal human fibroblasts." (PMID 24068928, 2013). "While the total level of ATM remained constant throughout the course of infection, the level of ATM-pS1981 increased dramatically by 2 days post infection (dpi)." (PMID 22952448, 2012). "RPTE cells were first transfected with siRNAs that targeted ATM, followed by infection with BKPyV when the knockdown of ATM was achieved at 3 days post transfection (dpt)." (PMID 22952448, 2012). "Recent work from our laboratory indicates that RVFV infection causes opposing activation of ATM and ATR pathways, where ATM and chk2 phosphorylation are up-regulated at 24 hours post-infection, whereas ATR phosphorylation is down-regulated." (PMID 22574148, 2012). "As observed in HEL fibroblasts, infections of normal dermal fibroblasts showed partially overlapping co-immunostaining for phospho-ATM and γH2AX." (PMID 21589897, 2011). "Here we show that HCMV replication is compromised in cells with inactivated or depleted ATM and that ATM is essential for the host DDR early during infection." (PMID 21589897, 2011). "It appears that ATM activation represents a general response to infection by DNA viruses or viruses that have a DNA stage in the replication strategy, such as retroviruses." (PMID 21589897, 2011). "Most of these viruses have in common infection-associated E2F deregulation, DDR activation, and a contribution of ATM to productive infections." (PMID 21589897, 2011). "Collectively, theseglobal gene expression analyses corroborate our findings of a period ofhyper-proliferation and activation of an ATM-dependent DNA damage response earlyafter infection that is attenuated during LCL outgrowth." (PMID 21147465, 2010). "The continuouspresence of either ATM or Chk2 inhibitor led to a dose dependent increase in Bcell number at two weeks post infection." (PMID 21147465, 2010). "We observed that levels of the Mre11 component of the MRN complex, which is associated with ATM activation, were reduced approximately 3-fold by 24 hrs following MVM infection of A9 cells." (PMID 20949077, 2010). "The primary role played by ATM following MVM infection is similar to that reported following infections with other viruses such as human papillomavirus HPV, SV40 and HSV." (PMID 20949077, 2010). "Since the DDR peaked during the first week after infection, we assessedwhen ATM and Chk2 inhibition enhanced proliferation and transformation." (PMID 21147465, 2010). "By Western analysis, the levels of ATM protein overexpression occurred by 24 hours following infection with the wild-type strain of A. actinomycetemcomitans." (PMID 20668524, 2010). "Importantly, treatment with caffeine or ATM/ATR-specific inhibitors reduced Vpr-enhanced mCherry expression to that of control infection." (PMID 39975144, 2025). "Since ATM is activated during KOS infection (20, –, 22) and USP15 is required for efficient HSV DNA replication, we hypothesized that USP15 would also be phosphorylated." (PMID 40824090, 2025).
infection (continued). "Focusing on DNA damage-related responses in RH strain infections, especially the ATM-related branch of the homologous recombination (HR) pathway was activated in primary host cells whilst molecules of the non-homologous end joining (NHEJ) pathway were either not affected or even found downregulated." (PMID 38524184, 2024). "Similarly, ATM-AVI was active against isolates from infection sources (MIC90 0.5–4 μg/mL) with ≥90.9% of isolates inhibited by ATM-AVI at ≤8 μg/mL globally and across regions (data limited to small number of isolates in North America (n ≤ 18))." (PMID 37998793, 2023). "We found that induction of DDR occurred following rAAV2.5T infection, which was characterized by the phosphorylation of replication protein A32 (RPA32) and histone variant H2AX (H2A histone family member X), as well as all three PIKKs: ATM, ATR, and DNA-PKcs." (PMID 37841417, 2023). "Here, we found that PEDV infection activates the ATM signaling at the late infection stage." (PMID 36016404, 2022). "EVA71 might induce DNA single-strand breaks to activate the ATR pathway which is responsible for the formation of γ-H2AX after EVA71 infection whereas the activation of ATM or DNA-PK might be lowered after EVA71 infection." (PMID 35067196, 2022). "Taken together, these data strongly suggest that the modulation of the cell cycle mediated by Rck is dependent on the DDR process and notably the ATR and/or ATM pathways, which are triggered in response to the DNA damage generated in the host DNA upon infection." (PMID 33330131, 2020). "This yet unproven hypothesis is supported by the finding that DDR sensors and effectors such as Mre11, Mdc1, and ATM colocalized with viral genomes early during infection." (PMID 32906746, 2020). "However, pathway analysis indicated that Apoptosis, ATM Signaling, and Cell Cycle: G2/M DNA Damage Checkpoint Regulation were exclusively regulated following infection with the virulent strain." (PMID 31800570, 2019). "Expression of rAAV8biΔBC-Gluc was only slightly affected by the ATM inhibitor 48 h post-infection." (PMID 28710345, 2017). "Whereas BMDMs with isolated deficiencies of ATM or DNA-PKcs exhibit a robust DDR, those with deficiencies in both ATM and DNA-PKcs (Scid:AtmC/C:Lyz2Cre/+) exhibit a near-complete abrogation of γ-H2AX and p-KAP-1 formation in response to infection with L. monocytogenes." (PMID 28362262, 2017). "Numerous studies have demonstrated that HPV exploits both the ataxia-telangiectasia mutated (ATM) and ataxia-telangiectasia and rad3-related (ATR) DDR pathways to replicate its genome and maintain a persistent infection by downregulating the innate and cell-mediated immunity." (PMID 29257060, 2017). "We also observed that ATM activation by dl366* infection of HeLa cells occurred earlier than ATR activation (represented by Chk1 phosphorylation), suggesting that ATR is activated and could exert its effect only at the later stages of infection." (PMID 26867009, 2016). "However, since ATM is dispensable for infection of HFFs, the viral DNA must recombine by means other than canonical ATM-dependent homologous recombination, perhaps through proteins that can complement ATM’s function." (PMID 26817608, 2016). "ATM and ATR deficiency as well as E4orf4 expression enhance infection efficiency." (PMID 26867009, 2016). "In summary, the ATM-Mre11 axis is induced at the MVC replication centers during infection." (PMID 24641873, 2014). "However, at 6 hours of infection, the mean fluorescence detected in cells treated with the ATM inhibitor was more than twice that of untreated cells." (PMID 25340842, 2014).